ACAD11 (acyl-CoA dehydrogenase family member 11)
Description:
Participates in fatty acid beta-oxidation (FAO) and energy production in the central nervous system (CNS), and to a lesser extent in the liver. Catalyzes the first step in FAO, which consists in the proR-proR stereospecific alpha,beta-dehydrogenation of fatty acyl-CoA thioesters using the electron transfer flavoprotein (ETF) as their physiologic electron acceptor, with maximal activity towards saturated docosanoyl-CoA (CoA 22:0) in both the cerebellum and the liver. Among the different mitochondrial acyl-CoA dehydrogenases, its FAO activity overlaps with that of ACADV and ACADL, but plays a primary role in tissues where it is the main long-chain ACAD expressed, such as the CNS, where together with ACAD9, they accommodate the full spectrum of long chain fatty acid substrates.
Synonyms: ACAD-11; FLJ12592
Tractability: Small molecule: a structure with a bound ligand is known; it has a high-quality binding pocket. PROTAC: its protein half-life has been measured; a small molecule that binds it is known.
Target class: Enzyme; Oxidoreductase
Gene: Protein-coding gene on chromosome 3 (132,558,138 to 132,660,104, reverse strand). Ensembl gene ENSG00000240303.
Subcellular location: Peroxisome; Mitochondrion membrane
Pathways (Reactome):
Metabolism: Mitochondrial Fatty Acid Beta-Oxidation
Gene Ontology:
Molecular function: acyl-CoA dehydrogenase activity; long-chain fatty acyl-CoA dehydrogenase activity; medium-chain fatty acyl-CoA dehydrogenase activity; protein binding; very-long-chain fatty acyl-CoA dehydrogenase activity; kinase activity; flavin adenine dinucleotide binding; oxidoreductase activity, acting on the CH-CH group of donors
Biological process: fatty acid beta-oxidation using acyl-CoA dehydrogenase; fatty acid catabolic process; fatty acid beta-oxidation
Cellular component: mitochondrial membrane; nucleus; peroxisome; cytoplasm; mitochondrial inner membrane; mitochondrion
Genetic constraint (gnomAD): Loss-of-function variants: 62 observed, 75.85 expected, observed/expected ratio (o/e) 0.82, 90% interval 0.67 to 1.01. The upper end of that interval is the gene's LOEUF score, 1.01, which puts it in group 4 of 6, group 1 being the genes least tolerant of losing a copy. Missense variants: 746 observed, 806.36 expected, observed/expected ratio (o/e) 0.93, 90% interval 0.87 to 0.98. Synonymous variants: 278 observed, 277.94 expected, observed/expected ratio (o/e) 1, 90% interval 0.91 to 1.11.
Homologues: Orthologues: chimpanzee ACAD11 (99% identical), macaque ACAD11 (95% identical), dog ACAD11 (86% identical), pig ACAD11 (84% identical), guinea pig ACAD11 (81% identical), mouse Acad11 (81% identical), rat Acad11 (81% identical), rabbit ACAD11 (80% identical), tropical clawed frog acad11 (67% identical), zebrafish acad11 (63% identical), Caenorhabditis elegans acds-10 (44% identical). Paralogues in human: ACAD10 (46% identical), ACADS (15% identical), ACADVL (14% identical), ACAD9 (13% identical), ACADSB (13% identical), ACADM (13% identical), ACAD8 (13% identical), ACADL (12% identical), IVD (12% identical), GCDH (11% identical), ACOX3 (10% identical), ACOXL (10% identical), and 2 more.
Diseases named in the same sentence as ACAD11 in open-access papers:
ACAD11 is named in the same sentence as 10 diseases in open-access papers, as found by Europe PMC text mining. Sharing a sentence is not in itself a finding about the gene and the disease. The quoted sentences say what the papers report.
osteoporosis (1 paper, 2024). A condition of reduced bone mass, with decreased cortical thickness and a decrease in the number and size of the trabeculae of cancellous bone (but normal chemical composition), resulting in increased fracture incidence. "Our study performed a comprehensive analysis of important EMGs in osteoporosis and developed a diagnosis signature consisting 5 EMGs, including B4GALT4, ADH4, ACAD11, B4GALT2, and PPP1R3C with a relative higher AUC." (PMID 38589566, 2024). "Overall, this study constructed a model that can predict the incidence of osteoporosis and identified B4GALT4, ADH4, ACAD11, B4GALT2, and PPP1R3C as potential biomarkers for osteoporosis development." (PMID 38589566, 2024). "B4GALT4, ADH4, ACAD11, B4GALT2, and PPP1R3C may be valuable biomarkers for the development of osteoporosis." (PMID 38589566, 2024). "Thus, we propose that B4GALT4, ADH4, ACAD11, B4GALT2, and PPP1R3C are involved in the development of osteoporosis, potentially by modulating metabolic pathways." (PMID 38589566, 2024).
tumor (5 papers, 2021 to 2025). "The expression level of ACAD11 was positively correlated with tumor purity and the infiltration levels of CD8+ T cells and B cells, but not with the infiltration levels of CD4+ T cells, dendritic cells, macrophages, and neutrophil." (PMID 34868460, 2021). "In ccRCC, ACAD11 was identified as an important prognosis-related gene, and its expression level was closely related to the infiltration of various immune cells in the tumor microenvironment." (PMID 41487520, 2025). "However, in contrast with non-tumour tissues, mRNA levels of Cpt1a, Acad11 and Srebp1c were downregulated in mouse HCC." (PMID 39203941, 2024). "Therefore, ACAD11 potentially plays a crucial role in the context of tumor advancement." (PMID 38297313, 2024). "mRNA levels of Ascl4 were not significantly different between groups, although there was a pattern of increased expression in tumours from C/C and HF/C animals, while levels of Cpt1a, Acad11 and Srebp1c were all significantly decreased in C/C and HF/C tumours relative to non-tumour tissues." (PMID 39203941, 2024).
cancer (3 papers, 2017 to 2025). A tumor composed of atypical neoplastic, often pleomorphic cells that invade other tissues.
infection (1 paper, 2025). The state of being infected such as from the introduction of a foreign agent such as serum, vaccine, antigenic substance or organism. "This interpretation is further supported by our time-resolved immunofluorescence analysis, which revealed that ACAD11 is recruited to the inclusion membrane only at late infection stages." (PMID 41124021, 2025). "In addition, we confirmed this interaction under native infection conditions through coimmunoprecipitation of Cps0558 followed by western blot, detecting ACAD11 as a specific interactor during infection." (PMID 41124021, 2025). "We hypothesize that the membrane-proximal recruitment of ACAD11 by Cps0558 during late infection supports inclusion maintenance while preserving essential host cell functions, thereby promoting prolonged host cell survival." (PMID 41124021, 2025). "The Pearson’s coefficient, ranging from −1 (mutual exclusion) to +1 (perfect colocalization), increased significantly from 0.003 ± 0.05 at 24 h p.i. to 0.3812 ± 0.0519 at 48 h p.i., indicating the interaction of ACAD11 and CPS0558 at the inclusion membrane during late stages of infection." (PMID 41124021, 2025). "Quantitative analysis of Cps0558 and ACAD11 colocalization by Pearson’s correlation coefficient showing a moderate but significant increase in Pearson’s correlation coefficient from 24 to 48 h p.i., independent of plasma membrane curvature at late stages of infection." (PMID 41124021, 2025).
ACAD11 also shares sentences with these, for which no sentence is quoted: Fanconi anemia (1 paper); Insulin resistance (1); metabolic disorders (1); neurological diseases (1); pancreatic cancer (1); theileriasis (1).